ADAR (adenosine deaminase RNA specific)
Diseases named in the same sentence as ADAR in open-access papers (continued):
Sharing a sentence is not in itself a finding about the gene and the disease.
bladder cancer (6 papers, 2017 to 2024). "ADAR is associated with the aggressiveness of some cancers, especially bladder cancer." (PMID 37414093, 2023). "Furthermore, in our collected clinical samples, ADAR was significantly upregulated in bladder cancer tissues and was associated with poor patient survival." (PMID 37414093, 2023). "Finally, we demonstrated that ADAR is a key pathogenic factor in bladder cancer." (PMID 37414093, 2023). "The protein levels of ADAR in 8 pairs of bladder cancer tissues (T) and adjacent normal tissues (N) were detected by western blotting, and the results were consistent with those obtained by qRT-PCR." (PMID 37414093, 2023). "ADAR was significantly upregulated in bladder cancer tissues, which was consistent with the bioinformatics analysis results." (PMID 37414093, 2023). "ADAR was also upregulated in five bladder cancer cell lines (T24, RT4, 5637, 253J and BIU87) compared with SVHUC-1 (human ureteral epithelial immortalized cell line, as the normal urothelial cell line)." (PMID 37414093, 2023). "CCK-8 assays showed that ADAR knockdown significantly inhibited the proliferation of bladder cancer cells." (PMID 37414093, 2023). "In endometrial cancer, bladder cancer and uterine endometrioid carcinoma, almost all ADAR gene alterations were amplification." (PMID 37414093, 2023). "Taken together, these in vitro experiments demonstrated that ADAR plays a key role in promoting the proliferation, migration, and invasion of bladder cancer cells, thus promoting the progression of BLCA." (PMID 37414093, 2023). "To further investigate the causes of miRNA editing events in bladder cancer, we compared the expression levels of the ADAR (ADAR1) gene in recurrent and primary BC using RT-qPCR." (PMID 36199571, 2022). "We first investigated the specific molecular pathways by which ADAR may be involved in bladder cancer by bioinformatics analysis." (PMID 37414093, 2023). "Finally, we performed a migration assay (wound healing), and the results showed that downregulation of ADAR inhibited the migration ability of bladder cancer cells, while upregulation of ADAR achieved the opposite effect." (PMID 37414093, 2023). "ADAR promoted proliferation and metastasis of bladder cancer cells." (PMID 37414093, 2023). "Moreover, in vitro experiments showed that ADAR effectively promoted the proliferation, migration, and invasion of bladder cancer cells." (PMID 37414093, 2023). "Finally, we specifically explored the potential value of ADAR in the treatment of the bladder cancer immune response and verified the critical role of ADAR in the development and progression of bladder cancer through experiments." (PMID 37414093, 2023). "ADAR plays an important role in the disease progression and immunotherapy of bladder cancer." (PMID 37414093, 2023). "We examined the expression of ADAR in bladder cancer tissues (n = 40) and matched adjacent normal tissues (n = 40) by qRT-PCR." (PMID 37414093, 2023). "The link between ADAR and inflammation in cancer and the role of BCG in treating bladder cancer may be interesting to explore in the future." (PMID 35930640, 2022).
depression (5 papers, 2019 to 2025). "PDE8A isoform B, which is by far the major isoform observed in blood, was significantly decreased in patients, while at the same time an increase in the non edited isoform was observed, suggesting a modification in either ADAR expression, activity, or subcellular localization in depression." (PMID 33931591, 2021).
HCMV infection (5 papers, 2014 to 2025). "While this dataset did not allow us to directly evaluate editing rates due to the lack of sequencing data and resultant inability to perform variant calling, it provided a large, clinical sample to evaluate the changes in expression of ADAR genes caused by congenital HCMV infection." (PMID 37968596, 2023). "Thus we concluded that following HCMV infection ADAR-p110 is induced, miR-376a is edited and that the edited miRNA, miR-376a(e), regulates the expression of HLA-E." (PMID 24586166, 2014).
chordoma (4 papers, 2015 to 2024). Chordomas are rare malignant tumors arising from embryonic remnants of the notochord in axial skeleton. "One such pathway affected, particularly with loss-of-function mutations in ADAR, is interferon-stimulated genes, and the study did in fact find elevated levels of interferon expression in chordoma, which enhances chordoma cell viability." (PMID 38892063, 2024). "Furthermore, the conditioned media from ADAR-deficient cells was sufficient to reduce proliferation of parental chordoma cells, suggesting that paracrine mechanisms contribute to sg-ADAR-induced lethality and can act independently of ADAR gene suppression." (PMID 37024492, 2023). "We assayed IFN-β secretion induced by ADAR depletion by measuring IFN-β levels in the conditioned media of sg-ADAR-treated chordoma cells." (PMID 37024492, 2023). "We find genomic and transcriptomic features that predict specific dependencies, including interferon-stimulated gene expression, which correlates with ADAR dependence and is elevated in chordoma." (PMID 37024492, 2023). "It remains to be determined whether these elements contribute to chordoma cells’ high expression of ISGs and consequent dependence on ADAR." (PMID 37024492, 2023). "Genes were selected to represent both those functionally connected to other chordoma dependency genes (PTPN11, FANCM, ADAR, PRKRA, SOX9, SRRM2, SLC2A1, and SLC7A5), as well as those with putatively unique effects (LUC7L2 and CDK6)." (PMID 37024492, 2023).
Dystonia (4 papers, 2014 to 2024). An abnormally increased muscular tone that causes fixed abnormal postures. "Particularly, bilateral striatal necrosis (BSN) is apparently exclusively seen in the context of ADAR1 (adenosine deaminase RNA specific) mutations, presenting as a subacute onset (days/weeks) of severe dystonia at a few months of age or in later childhood." (PMID 39424561, 2024).
mesothelioma (4 papers, 2020 to 2025). A usually malignant and aggressive neoplasm of the mesothelium which is often associated with exposure to asbestos. "Studies focused on mesothelioma development reported that, in mice, chronic exposure to asbestos significantly increased ADAR editing in tumors ⁠." (PMID 40362314, 2025). "The aim of this study was to characterize the ADAR‐dependent RNA editing landscape in human mesothelioma and put it into context with known BAP1 status." (PMID 36221913, 2022). "In this study, we show that ADAR‐dependent RNA editing increases in human mesothelioma similarly to what we had observed in the experimental model of mesothelioma development in mice exposed to crocidolite." (PMID 36221913, 2022). "The destabilization of dsRNA structures upon ADAR activity suppresses the cellular response to dsRNA by preventing type‐1 IFN signaling, and the TCGA study has revealed that in mesothelioma this activation occurs in tumors with mutated BAP1." (PMID 36221913, 2022). "The aim of this study was to characterize and assess the role of ADAR‐dependent RNA editing in mesothelioma." (PMID 36221913, 2022). "We found that tumors and mesothelioma primary cultures have higher ADAR‐mediated RNA editing compared to mesothelial cells." (PMID 36221913, 2022). "We observed that the sequence motif is consistent with the ADAR‐dependent editing signature as we had previously observed in mouse mesothelioma, confirming that RNA deamination is dysregulated in human mesothelioma." (PMID 36221913, 2022). "Increased adenosine deaminase acting on dsRNA (ADAR)-dependent editing of Alu elements in the RBM8A 3′UTR was observed in mesothelioma cells compared to mesothelial cells." (PMID 34944051, 2021). "Although two studies have shown either the existence of ADAR editing in mesothelioma development or growth suppression by silencing ADAR2 in one mesothelioma cell line, most functional studies remain to be performed on this cancer type." (PMID 33050791, 2020). "To characterize ADAR expression in mesothelioma cells, we determined mRNA and protein levels across a panel of 19 human mesothelioma cell lines, one SV‐40 immortalized human mesothelial cell line (MeT5A) and primary cells from normal human mesothelium (SDM104, SDM58, and SDM77)." (PMID 36221913, 2022). "Indeed, ADAR-dependent editing increases upon mesothelioma development, and in this study, we demonstrate that it participates in translational control in mesothelioma." (PMID 34944051, 2021). "Therefore, ADAR-dependent editing contributes to maintaining elevated RBM8A protein levels in mesothelioma by counteracting MSI2-driven downregulation." (PMID 34944051, 2021). "One of the targets of ADAR‐mediated editing is dihydrofolate reductase (DHFR) whose expression is regulated by editing in its 3'UTR and high editing levels are present in mesothelioma." (PMID 36221913, 2022). "In summary, ADAR-dependent RNA editing and ADAR expression, via their involvement in regulating type 1 IFN signalling, represent potential biomarkers and targets for mesothelioma immunotherapy for the treatment of mesothelioma, as has been shown for other cancers." (PMID 33050791, 2020).
Obesity (4 papers, 2024 to 2025). Accumulation of substantial excess body fat. "Proteomic profiling quantified identified 135 differentially expressed proteins (57 upregulated, 78 downregulated), with PHACTR2 and PLIN2 upregulated in obesity and ADAR down-regulated in obesity." (PMID 40822952, 2025). "Moreover, a pan-tissue, single-cell CRISPR-KO screen in teratomas unveiled ADAR’s integral role across all germ layers, with a distinct emphasis on adipogenic cell-fate determination, suggesting ADAR’s potential implication in obesity-related phenotypes." (PMID 39537590, 2024). "The link between ADAR dysregulation and adipogenesis could also motivate the development of therapeutics for obesity." (PMID 39537590, 2024).
ZIKV infection (4 papers, 2020 to 2024). "In order to establish causality between ZIKV infection and post transcriptional modification due to ADAR expression, future mechanistic studies are necessary." (PMID 33133033, 2020). "Our RNA-seq data analyses provide evidence for changes in ADAR expression and editing caused by congenital infection by CMV and ZIKV in mice, and to a lesser degree, ZIKV infection of hiNPCs." (PMID 37968596, 2023). "The evidence presented here is consistent with the hypothesis that congenital CMV and ZIKV infection induces changes in ADAR editing, which in turn disrupts brain development." (PMID 37968596, 2023).
Aicardi-Goutières Syndrome type 6 (3 papers, 2022 to 2025). "The homozygous variant c.2908G > A (p.Ala970Thr) in the ADAR gene causes Aicardi-Goutières Syndrome type 6." (PMID 39732715, 2024).
brain tumors (3 papers, 2009 to 2020). "All 3 editing mediating enzymes, ADAR1 (ADAR), ADAR2 (ADARB1), and ADAR3 (ADARB2), is downregulated in brain tumors and ADARB2 is also negatively correlated with GBM grades." (PMID 32244981, 2020).
breast tumors (3 papers, 2015 to 2025). "Given that we have shown that both ADAR expression and mean editing frequency were higher in breast tumors compared to matched normal tissues, we aimed to further investigate ADAR’s role on cell proliferation, migration, and apoptosis." (PMID 26440892, 2015). "Additionally, correlation of high ADAR protein levels with poor relapse free survival in ER (+) breast tumors warrant further investigation." (PMID 40381037, 2025).
squamous cell carcinoma (3 papers, 2017 to 2023). A carcinoma arising from squamous epithelial cells. "IGFBP7 transcripts are highly edited in the normal epidermis, while this editing is significantly reduced in basal cell and squamous cell carcinomas; 4) A-to-I is regulated by the ADAR enzyme RNA editing, thereby regulating the editing level of oncogenes and regulating the development of cancer." (PMID 34899345, 2021).
thyroid (3 papers, 2020 to 2025). "In our study, the results indicated TRIM47 endorses thyroid tumorigenesis via the down-regulation of ADARviaTRIM47/ADAR axis as well, which involved GSK-3β mediated phosphorylation." (PMID 40618019, 2025).
Hypertension (2 papers, 2017 to 2025). The presence of chronic increased pressure in the systemic arterial system. "Moreover, we verified AMOT, PLEKHH3, ADAR, BIRC3, and LGALS3 protein over-expressions in the treatment-naïve OSA patients, and discovered a correlation between AMOT/BIRC3/LGALS3 protein expression and the presence of EDS/hypertension/CKD, respectively." (PMID 28520763, 2017).
Infertility (2 papers, 2022 to 2024). "ADAR mutations in Drosophila have been reported to cause male sterility, but it is unclear which stage of spermatogenesis is specifically affected by ADAR and the mechanisms that cause infertility." (PMID 38891830, 2024).
mesenchymal tumors (2 papers, 2020 to 2022). "We identify distinct editing patterns between epithelial and mesenchymal tumors in seven cancer types using TCGA data, an observation further supported by single-cell RNA sequencing data and ADAR perturbation experiments in cell culture." (PMID 33106178, 2020).
neuroblastoma (2 papers, 2018 to 2023). Neuroblastoma (NB) is the most common solid, extracranial childhood tumor. "A fourth piece of evidence for the relationship between ADAR-mediated A-to-I editing and altered TDP-43 levels originates from knockdown experiments in Caenorhabditis elegans, HeLa cells, and M17 neuroblastoma cells." (PMID 29875629, 2018).
psoriasis (2 papers, 2019 to 2023). An autoimmune condition characterized by red, well-delineated plaques with silvery scales that are usually on the extensor surfaces and scalp. "Interestingly, ADAR was significantly upregulated in lesional skin both when considering the RNA-seq data and the NanoString nCounter data in both psoriasis cohorts." (PMID 31775754, 2019).
allergic asthma (1 paper, 2025). A asthma with a basis in a pathological type I hypersensitivity reaction. "We find that genes with many connections in this network representation, such as ADAR, PAN3, and MAPK1 have been implicated in allergic asthma before (50, –52)." (PMID 40504147, 2025).
benign ovarian tumors (1 paper, 2016). "ADAR expression levels have been reported to be significantly higher in serum and/or peritoneal fluid from patients with EOCs compared with benign ovarian tumors." (PMID 27911851, 2016).
cerebrovascular disease (1 paper, 2023). "There are several classic AGS subtypes with prenatal and infantile-onset: spastic-dystonic syndrome, ADAR-1-related bilateral striatal necrosis, hereditary spastic paraparesis, and SAMHD-1-related cerebrovascular disease." (PMID 37371788, 2023).
cervical tumor (1 paper, 2023). "In our research, we observed a significant downregulation of ADAR in cervical tumor tissues, while Helicase, OAS_RNAsel, PKR, and RLR were upregulated." (PMID 37735483, 2023).
Duchenne muscular dystrophy (1 paper, 2023). Duchenne muscular dystrophy (DMD) is a neuromuscular disease characterized by rapidly progressive muscle weakness and wasting due to degeneration of skeletal, smooth and cardiac muscle. "While there have been reports of using Mini-dCas13X for Duchenne muscular dystrophy, RNA base editors recruiting endogenous ADAR for diseases with target tissues outside the liver have yet to be tested." (PMID 37293541, 2023).
Epstein-Barr virus infection (1 paper, 2023). An infection that is caused by Epstein-Barr virus. "GO and KEGG enrichment analyses of differentially expressed genes showed that the highly expressed ADAR group was significantly enriched in Epstein Barr virus infection and influenza A pathways; it was also related to the defense response to virus and response to virus." (PMID 37414093, 2023).
herpesvirus infection (1 paper, 2023). "Although much is already known about the role of ADAR proteins in RNA virus infection, the role of ADAR proteins in herpesvirus infection remains largely unexplored." (PMID 37896783, 2023). "This review presents all currently published studies on ADAR-mediated posttranscriptional modifications and the potential role of ADARs in herpesvirus infection, major dsDNA viruses that have been largely neglected in A-to-I studies." (PMID 37896783, 2023). "The studies described have provided us with only a small glimpse of the possible role of ADAR proteins and the complexity they bring to herpesvirus infection." (PMID 37896783, 2023). "Sequence heterogeneity and potential editing phenomena in herpesviruses were first noted for KSHV, and only recently several studies on KSHV have shed light on the importance and diverse functions of ADAR proteins in herpesvirus infection." (PMID 37896783, 2023).
Insulin resistance (1 paper, 2025). Increased resistance towards insulin, that is, diminished effectiveness of insulin in reducing blood glucose levels. "ADAR plays a critical role in RNA editing, influencing metabolic gene expression, and its dysregulation may exacerbate insulin resistance." (PMID 40282289, 2025).
latent infection (1 paper, 2025). "Although we cannot completely rule out the importance of A-to-I editing during productive infection, the fact that HSV-1 miRNAs are hyperedited in latency strongly suggests a role for ADAR proteins in the regulation of at least latent infection." (PMID 40198737, 2025).
lymphoma (1 paper, 2022). A malignant (clonal) proliferation of B- lymphocytes or T- lymphocytes which involves the lymph nodes, bone marrow and/or extranodal sites. "We found that ADAR regulates cell proliferation and Rho GTPase inhibitor sensitivity of lymphoma." (PMID 35906682, 2022).
male infertility (1 paper, 2024). The inability of the male to effect fertilization of an ovum after a specified period of unprotected intercourse. "ADAR (adenosine deaminase acting on RNA) mutations in Drosophila cause male infertility, yet the causative factors remain unclear." (PMID 38891830, 2024). "Evidence exists linking Drosophila ADAR to male infertility and neurodegenerative disorders." (PMID 38891830, 2024). "By overexpressing ADAR in early germline cells, male infertility can be partially rescued." (PMID 38891830, 2024).
pharyngeal tumors (1 paper, 2025). "Subsite analysis revealed high ADAR expression correlated with poor OS in pharyngeal tumors (p < 0.05), whereas high ADARB2 expression was linked to improved DFS (pa = 0.0023, pb = 0.0047)." (PMID 41300768, 2025).
primary immunodeficiencies (1 paper, 2025). "This is supported by the fact that among the 38 interferon response genes (category II), only OAS1, ADAR, PSMB8, SAMHD1 and the IRF transcription factors have been implicated in causing primary immunodeficiencies." (PMID 41038828, 2025).
prion disease (1 paper, 2020). A transmissible disease that is caused by a protein that is able to induce abnormal folding of normal cellular proteins, leading to characteristic spongiform brain changes, which are associated with neuronal loss without an inflammatory response. "The expression levels of the ADAR enzymes, Adar1 and Adarb2 did not change during prion disease progression, whereas Adarb1 was significantly downregulated at the terminal stage." (PMID 32598380, 2020).
respiratory infections (1 paper, 2015). "In lung, for example, the IFN-inducible p150 ADAR isoform may be produced to protect against respiratory infections." (PMID 26449202, 2015).